RNU6-123P (RNA, U6 small nuclear 123, pseudogene)
Gene: Small nuclear RNA gene on chromosome 21 (25,943,044 to 25,943,145, reverse strand). Ensembl gene ENSG00000251972.
Homologues: Orthologues: chimpanzee U6 (100% identical), macaque U6 (95% identical), pig U6 (70% identical). Paralogues in human: RNU6-1031P (84% identical), RNU6-940P (84% identical), RNU6-1227P (82% identical), RNU6-1310P (82% identical), RNU6-140P (82% identical), RNU6-16P (82% identical), RNU6-24P (82% identical), RNU6-409P (82% identical), RNU6-43P (82% identical), RNU6-454P (82% identical), RNU6-46P (82% identical), RNU6-529P (82% identical), and 1282 more.